S100A8 (S100 calcium binding protein A8)
Diseases named in the same sentence as S100A8 in open-access papers (continued):
Sharing a sentence is not in itself a finding about the gene and the disease.
tumor (continued). "So far, S100A8/S100A9 has been described as a crucial factor for recruitment of MDSCs and immunosuppression in the tumor microenvironment." (PMID 36932197, 2023). "S100A8, an endogenous ligand of Toll-like receptor 4 (TLR4), is known as a key molecule in the tumor microenvironment and premetastatic niche formation." (PMID 36932197, 2023). "By releasing angiogenic factors including S100A8 and S100A9, as well as activating vascular endothelial growth factors A (VEGFA) in the extracellular matrix and MMP9, tumor angiogenesis was maintained by neutrophils." (PMID 36609243, 2023). "In tumors, pro-inflammatory S100A8/A9 production helps sustain MDSC accumulation for maintaining immune suppressive TME and facilitating tumor immune escape." (PMID 37256148, 2023). "Due to the increased Gr1+CD11b+Ly6G+ neutrophils and S100A8/A9 proteins, the lungs of BALB/c mice bearing 67NR, 4T07, or 4T1 tumor can actively recruit intracardially injected 4T1-Luc2-tdTomato metastatic breast cancer cells." (PMID 37553342, 2023). "RAGE, HMGB1, and S100A8/A9 are critical molecules for MDSC development and function, but they also have other mechanisms by which they promote tumor growth." (PMID 36831371, 2023). "Therefore, we assume that divalent peptide3A5 would provide anti-tumor activity with similar mechanism to Eritoran, which may improve the efficacy of anti-PD-1 antibody, and that multivalent S100A8 inhibitory peptides can be useful to improve the efficacy of other chemotherapeutic agents." (PMID 36932197, 2023). "The results showed that S100A8 and S100A9 mRNA increased significantly in tumor compared with normal breast tissue." (PMID 38093319, 2023). "EMMPRIN, also called CD147 or basigin, serves as a receptor for calprotectin in tumor cells and has a higher affinity for S100A9 than that for S100A8." (PMID 37701037, 2023). "The GEPIA2 data indicate that both S100A8 and S100A9 were more highly expressed in the tumor issues than in the normal tissues." (PMID 37629174, 2023). "Meanwhile, exogenous S100A8/A9-induced ERK1/2 phosphorylation can promote the proliferation and invasion of tumor cells." (PMID 37701037, 2023). "Besides the apparent differences in tumor histology, these tumor models also exhibited variable infiltration of myeloid cells, including macrophages and neutrophils, as illustrated by the immunostaining of F4/80 (macrophage marker) and S100A8 (neutrophil marker), respectively." (PMID 37874652, 2023). "We previously showed that S100A8 is an endogenous TLR4 ligand, and that an anti-S100A8 neutralizing antibody can suppress tumor progression in tumor-bearing mice." (PMID 36932197, 2023). "We then explored the crucial biomarkers of MRS1-tumor cells, finding that S100A7, S100A8, and PTTG1 were up-regulated in the MRS1 phenotype both in bulk data (TCGA-BLCA and GSE13057) and single-cell data." (PMID 37543645, 2023). "In the tumor array, correlations were observed between S100A9 and S100A8 (R = 0.62), S100A4 (R = 0.78), S100A10 (R = 0.51), S100A12 (R = 0.76), and HMGB1 (R = 0.80)." (PMID 37627239, 2023). "For this reason, S100A8 and S100A9 can be found in tumor tissues that are infiltrated with immune cells, where they act as chemo-attractants for other immune cells and can promote an inflammatory tumor micro-environment." (PMID 37627239, 2023). "All these data support the important role of extracellular S100A8/S100A9 in regulation of the microenvironment and its potential involvement in tumor progression." (PMID 36923707, 2023). "First, S100A8/S100A9 promotes tumor cell growth through the activation of the NF-κB signaling pathway in a RAGE-dependent manner, while S100A8/S100A9 can interact with RAGE." (PMID 37346040, 2023). "The impact of RAGE and its principal ligands S100A8/A9 and HMGB1 on multiple aspects of tumor progression has been established in numerous and diverse mouse and human cancers." (PMID 36831371, 2023).
tumor (continued). "The reduction in neutrophil infiltration by zotatifin was also confirmed by immunostaining for the neutrophil marker S100A8 in 2153L, 2225L-LM2, and 2208L tumor tissues." (PMID 37874652, 2023). "Intratumoral knockdown (KD) of Serpinb3a resulted in tumor growth inhibition and reduced CXCL1 and S100A8/A expression and MDSC and M2 macrophage infiltration." (PMID 37279067, 2023). "This article reviews the involvement of RAGE, S100A8/A9, and HMGB1 in tumor progression and how these molecules impact MDSC development, half-life, and function." (PMID 36831371, 2023). "S100A8 and S100A9 are two proinflammatory cytokines through which many of the molecules secreted by the primary tumor in response to hypoxia exert their function." (PMID 36497411, 2022). "Although the infiltration of MDSCs expressing S100A8 and S100A9 has been closely related to tumor stage, lymph node metastases, and poor prognosis, there is a rising evidence that CD147+ myeloid cells are key players in HPV-driven cancers." (PMID 36303837, 2022). "We found that Eritoran blocked S100A8-mediated TLR4 activation and reduced TAMs and CD11b+Ly6C++Ly6G− populations in tumor microenvironment." (PMID 35780158, 2022). "The S100 protein family members, S100A8A/S100A9, which form an S100A8/A9 heterodimeric complex able to interact with both TLR4 and RAGE on tumor cells, are also key in promoting RAGE-mediated inflammatory responses." (PMID 35727208, 2022). "The Calprotectin subunits S100A8 and S100A9 as well as the receptor CD147 were elevated expressed in PeCa compared to non-malignant tissue, with a markedly higher expression at the tumor core and lymph node metastases." (PMID 36303837, 2022). "Neutrophil-derived MDSCs, in turn, release S100A8 and S100A9 to sustain tumor angiogenesis and to create a pre-metastatic niche by facilitating the extravasation and growth of metastasis-initiating cells." (PMID 36303837, 2022). "Previously, we reported that the CRT fragment (recombinant sCRT/39-272) promoted tumor malignancy through TLR4- and S100A8/9-mediated MDSC differentiation and recruitment." (PMID 36249426, 2022). "Numbers of S100A8/A9+ and S100A12+ cells were highly correlated in tissues of UC dogs (ρ = 0.96, P < 0.0001) and in dogs with non-neoplastic disease (ρ = 0.94, P = 0.0048)." (PMID 36411489, 2022). "TAMs and CAFs were classified according to their tumor origin and high expression of SPP1, C1QB, IL1B, S100A8, S100A9 and type I collagens (COL1A1 and COL1A2)." (PMID 36209225, 2022). "Neutrophils have been shown to support tumor angiogenesis via the release of numerous pro-angiogenic factors, such as VEGF, FGF-2, oncostatin M, IL-17, MMP-9, Bv8, S100A8/9 alarmins, STAT3, and NETs." (PMID 35158807, 2022). "There is an increasing evidence for distinct functions of S100A8 and S100A9 if expressed as intracellular and extracellular by tumor or immune cells." (PMID 36303837, 2022). "S100A8 and S100A9 are also highly expressed in TME mast cells which promote tumor proliferation and metastasis and indicate poor outcomes according to previous research." (PMID 36148946, 2022). "It was recently reported that S100A4 enhanced the expression of mouse SAA1 and SAA3, which stimulated expression of RANTES, G-CSF, MMP2, S100A8, and S100A9 to promote tumor metastasis." (PMID 35936690, 2022). "RAGE is a key receptor of S100A8 and S100A9 in tumor cells, whereas TLR4 is a major receptor for both these ligands in macrophages." (PMID 36613714, 2022). "S100A8/S100A9 proteins released by phagocytes also contributed to the early recurrence of cancer and tumor invasion." (PMID 35741108, 2022). "They detected S100A9 monomers, S100A8/S100A9 heterodimers and S100A9 homodimers intracellularly in spleen cells of tumor bearing animals while only S100A9 monomers and homodimers were secreted." (PMID 35198063, 2022).
tumor (continued). "MG and tumor tissues than in WTMG and WT tumor tissues were further confirmed by immunohistochemistry (IHC) with antibodies against S100a8 and S100a9, which are the markers for MDSCs." (PMID 35304461, 2022). "Pro-angiogenic factors that are released by neutrophils, such as VEGF, Bv8, MMP-9, and S100A8/S100A9, directly induce tumor angiogenesis via the activation of endothelial cell proliferation." (PMID 35158807, 2022). "Combinatorial induction of IL6 and S100A8/A9 in the TME and ICAM-1 and IL8 in the CDX tumor comprise a positive feedback loop that drives inflammation." (PMID 34010296, 2021). "Combinatorial induction of IL6 and S100A8/A9 in the Hltf-deleted TME with ICAM-1 and IL8 in the primary tumor activated a positive feedback loop." (PMID 34010296, 2021). "S100A8/9 dimers were reported to promote tumor cell proliferation by creating a pro-inflammatory microenvironment and contribute to disease progression in MPN, whereas tasquinimod, an S100A8/S100A9 inhibitor, inhibited the MPN phenotype." (PMID 34390367, 2021). "The effect of calprotectin on tumor cells is dependent on the concentration: at high concentrations, the heterocomplex of S100A8/S100A9 exerts an apoptotic effect, but at low concentrations, calprotectin promotes tumor cell growth." (PMID 33466593, 2021). "S100A8/A9 knockdown in the cancer cells reduces MMP-2 and MMP-9 expression that is closely related among other mediators to tumor cell migration and invasion." (PMID 33567747, 2021). "All these findings indicate that tumor exosomes containing S100A8 and S100A9 proteins suppresses DCs maturation and improves the premetastatic niche formation in tumor-draining lymph nodes." (PMID 34078376, 2021). "One established downstream mediator of S100A8/S100A9 signaling is MAPK, which upon phosphorylation can induce tumor cell migration; this is of particular interest because S100A8 is a chemotactic agent." (PMID 34975408, 2021). "S100A8 plays a significant role in TLR4/myeloid differentiation factor 2 (MD-2) pathway activation; thus, promoting a tumor growth-enhancing immune microenvironment." (PMID 33567747, 2021). "Overexpression of S100A8/A9 increased in vitro HCC cell survival, growth and invasiveness as well as xenograft tumor size in the mouse model." (PMID 34517344, 2021). "Proinflammatory S100A8 and S100A9, whose expression is induced by factors secreted from primary tumours such as TNF-α, TGF-β and VEGF-A, serve as recruiters of CD11b+ myeloid cells into the pre-metastatic lungs, in turn promoting metastasis formation." (PMID 35006432, 2021). "The expression levels of S100A8 and S100A9 were elevated in serum and tumor tissue samples from HCC patients." (PMID 34517344, 2021). "Moreover, both S100A8 and A9 proteins could inhibit tumor progression of xenograft model of CEL." (PMID 33801279, 2021). "As reported with S100A4, hypoxia regulates S100A8/A9 expression through the presence of an HRE in the promoter region of both S100A8 and S100A9 genes, suggesting that these two proteins contribute to tumor progression in hypoxic conditions." (PMID 34360919, 2021). "In this study, the proinflammatory mediator S100A8/A9 in combination with species-specific expression of proinflammatory cytokines IL6 (mouse) and IL8 (human) established a pro-metastatic primary tumor niche in the Hltf-deleted TME." (PMID 34010296, 2021). "Neutralizing anti-S100A8 and anti-S100A9 antibodies blocked the morphological changes and migration of CD11b/CD18 positive myeloid cells into the lungs of tumor-bearing mice through p38 signaling." (PMID 34201758, 2021). "The roles of S100A8 and S100A9 have been studied in many tumor models (colon, breast, neuroblastoma, etc.)and seems to be dual." (PMID 33801279, 2021). "Displaying expression levels in the tumor vs. in the healthy stroma revealed a clear accumulation of S100A8 and S100A9 in the tumor, similar to that observed in the MS images." (PMID 32733643, 2020).
tumor (continued). "After a series of validation experiments for the concerned genes, it was found that IL6, GM‐CSF (CSF2), IL11, CCL3, S100A8 and S100A9 were significantly decreased in the gut tumours of ApcMin/+ TLR4−/− mice compared with ApcMin/+ WT mice." (PMID 31650683, 2020). "Comparing the tumor to the healthy epithelium, the expression level of S100A8 and S100A9 in the tumor appeared slightly higher, which was found statistically significant." (PMID 32733643, 2020). "With a sizeable fraction of the examined samples showing clearly higher expression of S100A8 and S100A9 in the tumor vs. in the tumor stroma these tissue areas were statistically distinguishable." (PMID 32733643, 2020). "Altogether, imaging S100A8 or S100A9 expression allowed to differentiate the tumor tissue from the healthy stroma, and to a lesser extent distinguished between the tumor and the tumor stroma or the healthy epithelium." (PMID 32733643, 2020). "Growing studies have verified that heterocomplex of S100A8/S100A9 led to MDSC migration and mediated tumor cell invasion." (PMID 33117687, 2020). "Collectively, these results suggest that MDSC express S100A8/A9 and create the premetastatic niche in ME180-GCSF-derived tumor-bearing rats, leading to the false-positive detection of metastatic lymph nodes by 18F-FDG-PET/CT." (PMID 32170086, 2020). "S100A8/9 is overexpressed in MDSC in different types of cancer and its expression is correlated with tumor load." (PMID 31953577, 2020). "In contrast, the downregulation of CD146/ETV4 axis repressed S100A8/A9-induced EMT, resulting in greatly weakened tumor growth and lung metastasis." (PMID 32782280, 2020). "Although displaying a heterogenous distribution within the examined ROIs, expression of either S100A8 or S100A9 clearly distinguished between healthy stroma and tumor areas, and proved to be a statistically reliable positive tumor marker of the specimen." (PMID 32733643, 2020). "As recruited monocytes mature, they lose S100A8 and keep S100A9 expression and recruit more inflammatory cells, resulting in tumor cell proliferation and invasion." (PMID 33117687, 2020). "The calcium-binding pro-inflammatory proteins S100A8 and S100A9, which are ubiquitously present in the tumor microenvironment, drive the accumulation of MDSCs through increased recruitment to primary tumor and pre-metastatic niche." (PMID 32793192, 2020). "Selected regions of the neoplastic and healthy tissue areas were subjected to histopathological scoring for determining S100A8 and S100A9 expressions in the tumor, tumor and healthy stroma as well as in the healthy epithelium." (PMID 32733643, 2020). "Monocytes, known for their functional and molecular plasticity, can be recruited to the tumor site by tumor‐secreted chemo‐attractants (eg, CCL2, S100A8/S100A9), and polarized toward M1 or M2 macrophages depending on the cytokine milieu." (PMID 31033233, 2019). "The exact mechanism of S100A8/S100A9 in PMN formation is unclear, although S100A8/S100A9 is crucial for intercellular crosstalk between tumor and stromal cells during PMN establishment." (PMID 30792719, 2019). "Based on our data, the serum levels of both S100A8/A9 and CA15-3 were significantly higher in patients compared to the healthy controls, and thus positively correlated with tumor size." (PMID 31528166, 2019). "When the tumor suppressor gene SMAD4 is expressed by PDAC cells, S100A8 and S100A9 are produced by the tumor infiltrating inflammatory cells." (PMID 30764482, 2019). "In the 4T1 mammary and LLC lung carcinoma models, enhanced expression of pro-metastatic proteins in MDSCs, such as Bv8, MMP9, S100A8 and S100A9, facilitates improved PMN formation, which supports more efficient tumor cell extravasation and proliferation." (PMID 30792719, 2019). "The high correlation also indicated that S100A8 and S100A9 transcripts have potential to serve as surrogate markers for levels of stromal infiltration in tumor tissue." (PMID 30808902, 2019).
tumor (continued). "The calprotectin complex consisting of S100A8 and S100A9 proteins has recently been identified as key driver of chronic and tumor promoting inflammation in skin carcinogenesis." (PMID 29563902, 2018). "Neutralizing anti-S100A8 and anti-S100A9 antibodies blocked the morphological changes and migration of tumor cells and Mac 1-positive myeloid cells." (PMID 29416786, 2018). "Still, even small wounds to the tumor created by needle biopsy can rapidly promote pro-inflammatory factors such as S100A8, CXCL2, CCL3, and COX2 followed by a significant increase in the number of myeloid derived suppressor cells in the tumor." (PMID 29728948, 2018). "To exclude the influence from the tumor microenvironment, we also stained the serial section with both cytokeratin 7 (CK7) and S100A8." (PMID 30456203, 2018). "In turn, SAA stimulates its own transcription as well as that of the proinflammatory S100A8 and S100A9 proteins, strongly enhancing adhesion, migration and invasion of human and mouse tumour cells." (PMID 29788918, 2018). "S100A8 and S100A9 are induced by primary tumor and chemoattract CD11b+ bone marrow-derived cells in pre-metastatic lungs by us." (PMID 30167087, 2018). "Induction of S100A8 and S100A9 expression in response to primary lung tumor cell-derived soluble factors VEGF-A, TGF-β and TNF-α in myeloid cells prior to tumor metastasis has been reported." (PMID 30558665, 2018). "S100a8/a9 promotes the activation of MAPK or NF-κB signaling pathways and leads to tumor cell proliferation in CAC." (PMID 29326691, 2017). "These neutrophils contribute to the elevated levels of pro-metastatic molecules like S100A8, S100A9, Bv8, and MMP9 in the lungs, supporting tumor cell homing to this organ." (PMID 29340117, 2017). "TGF-β signaling is also a significant contributor in the metastatic environment through regulation of chemo-attractants S100A8, S100A9, and ANGPTL4, which enhance tumor cell invasion and disruption of vascular endothelial cell-cell junctions." (PMID 27223426, 2017). "Again, pro-inflammatory S100 proteins such as S100A8, S100A9 controls the trafficking and accumulation of MDSCs in tumor bearing host." (PMID 28414726, 2017). "In concert with CXCL1, S100A8/9 and IL-8 entrain IRISOE tumor cells to survive the harsh conditions within the niche (step 5) to become metastatic precursors." (PMID 29262555, 2017). "MDSC-derived S100A8/A9 and MMP9 can pre-dispose the lung microenvironment to promote tumor metastasis." (PMID 29142311, 2017). "Hiratsuka and colleagues showed that primary tumor cells release VEGF-A, TGFβ and TNFα that in turn, induces the expression of the chemoattractants such as S100A8 and S100A9 by lung endothelium and myeloid cells." (PMID 29340117, 2017). "Our data show that several S100 genes, i.e. S100A4, S100A6, S100A10, S100A8, and S100A9, are expressed at very high levels in both tumor cells and TAMs." (PMID 27215396, 2016). "Here we explored the significance of S100A8 and S100A9 induction by the myeloid cells in the tumor microenvironment." (PMID 27086923, 2016). "Our findings demonstrate that monocytes/macrophages in the metastatic liver microenvironment induce S100A8 and S100A9 in cancer cells, and that these proteins are essential for tumor cell migration and invasion." (PMID 27086923, 2016). "To determine the effects of S100A8 and S100A9 on tumor cell proliferation, migration and invasion, we downregulated both the genes in MC38 and LLC cells using lentiviral short hairpin RNA (shRNA)." (PMID 27086923, 2016). "S100A8 and S100A9 are known to influence tumor cell proliferation, survival, and migration as well as to stimulate migration and proliferation of neutrophils themselves." (PMID 28066438, 2016). "The results showed that the S100A8 overexpression in Huh7 and MHCC-97H cells induced marked increase in cell proliferation, migration, invasion, and tumor growth." (PMID 27462864, 2016).